IL10 (interleukin 10)
Diseases named in the same sentence as IL10 in open-access papers (continued):
Sharing a sentence is not in itself a finding about the gene and the disease.
Autoimmunity (continued). "Only one patient within the non-relapsed cohort developed secondary autoimmunity (microscopic colitis) at 2 months post-AHSCT and this was reflected in a brief elevation in the concentration of cytokines at 3 months, such as IFNγ and IL-10." (PMID 35126353, 2021). "In a recent study, CD19+CD24hiCD38hi Bregs from patients with SLE were found to be refractory to CD40 engagement and produced less IL-10 and lacked CD4+ T-cell suppressive capacity compared with the healthy controls, suggesting that functional defects of Bregs could lead to autoimmunity." (PMID 26209442, 2015).
depression (334 papers, 2006 to 2026). "According to network pharmacology results, IL-6, IL-1β, TNF-α, and IL-10 are closely associated with SD and depression." (PMID 40076470, 2025). "Where data was available, individual meta-analyses showed positive associations between IFN-γ and IL-10 and level of depression." (PMID 39867847, 2025). "Multivariate analysis identified PD-1 (OR = 3.32) and MMP-9 (OR = 2.18) as independent risk factors for depression, while IL-10 (OR = 0.62) and BDNF (OR = 0.12) emerged as protective factors." (PMID 40823578, 2025). "Administration of IL-10 has also been shown to reverse depression-associated learning and memory deficits in mice." (PMID 40436945, 2025). "A meta-analysis showed that higher concentrations of TNF-α, IFN-γ, IL-6 and IL-10 were significantly associated with higher levels of depression in individuals with MS (r = 0.35, 95% CI [0.6,0.03], p = .015." (PMID 39867847, 2025). "With the data available, significant associations between TNF-a, IFN-γ, IL-6 and IL-10 concentrations and level of depression were found suggesting that depression is associated with inflammatory responses in the immune system in individuals with MS." (PMID 39867847, 2025). "The analysis revealed that higher levels of BDNF (OR < 1) and IL-10 (OR < 1) were significantly associated with a reduced risk of depression, suggesting a protective neurotrophic and anti-inflammatory effect." (PMID 40823578, 2025). "•Meta-analysis showed association between TNF-a, IFN-g, IL-6 and IL-10 and depression in individuals with MS." (PMID 39867847, 2025). "None of the studies that have explored the association between IL-10 and depression found significant results." (PMID 38820411, 2024). "At 6 months post-TBI, increased plasma IL-10 levels were associated with greater depression and more severe PTSD symptoms." (PMID 38397895, 2024). "Six months after the injury, elevated plasma IL-10 levels were associated with greater depression scores and more severe PTSD symptoms." (PMID 38397895, 2024). "IL-10 impacts several symptoms associated with depression, namely, helplessness, sleep disturbances, and pain perception." (PMID 38731995, 2024). "Numerous studies using animal models have shown that IL-10 deficiency is associated with depression-like behavior, whereas IL-10 overexpression reduces it." (PMID 38646609, 2024). "There have been contradictory findings in relation to associations between serum the IL-10 level and depression." (PMID 39358787, 2024). "At the six month mark, elevated plasma IL-10 levels are associated with greater depression scores (p = 0.004) and more severe PTSD symptoms (p = 0.001)." (PMID 37251220, 2023). "Another way to measure depression-related biomarkers is through saliva where the anti-inflammatory cytokine IL-10 is significantly associated with depression severity in MS patients." (PMID 36360559, 2022). "Peripheral administration of IL-10 rescues depression-associated learning and memory deficits in mice." (PMID 35308288, 2022). "High IL-10 in RA is associated with an increased risk of depression, tocilizumab can reduce depressive symptoms." (PMID 36755665, 2022). "Decreased levels of IL-10 were described in humans with symptoms of depression, anxiety, and increased suicide risk in a population study, as well as in stroke patients who developed the depressive disorder." (PMID 36614020, 2022). "Certain inflammatory markers known to be elevated in persons with depression, such as interleukin-6 (IL-6) and interleukin-10 (IL-10) have been associated with disease severity and mortality in patients infected with SARS-CoV-2." (PMID 34066585, 2021). "Interleukin (IL)-1β, IL-6, IL-10, monocyte chemoattractant protein-1, tumor necrosis factor-alpha, C-reactive protein, and phospholipase A2 contribute to depression, which is also associated with type 2 diabetes." (PMID 34639601, 2021).
depression (continued). "For example, IL-10 knockout mice show increased depression-like behavior and administration of IL-10 rescued depression-associated learning and memory deficits in mice." (PMID 33921690, 2021). "Some meta-analyses have provided evidence that the alterations in the levels of peripheral cytokine (e.g., IL-8, TNF-α, IL-6, and IL-10) are associated with the antidepressant treatment response in patients with major depressive disorder (MDD)." (PMID 33488420, 2020). "Consistent with this, IL-10 levels have been shown to be diminished in depression, and a defective anti-inflammatory IL-10 pathway has been associated with resistance to antidepressant treatments." (PMID 32828124, 2020). "In terms of the IL-10 result, maladapted cytokine responses have long been implicated in psychological disorders, including depression and anxiety." (PMID 32298279, 2020). "Similar findings were reported in major depression showing significant associations between an immune activation index (based on IL-6 and IL-10) and KOR, MOR and β-endorphin levels." (PMID 32858974, 2020). "IL-10 is associated with depression in both lupus and rheumatoid arthritis, but whereas higher IL-10 levels correlate with depression in RA, lower levels correlate with depression in lupus." (PMID 30148175, 2018). "At the same time, depression on its own alters IL-1 and IL-10 levels, further causing a disequilibrium between pro- and anti-inflammatory markers which cause a change from normal health to provoke and/or perpetuate IBS symptoms." (PMID 30357038, 2018). "For example, genetic polymorphisms in IL-10 and IL-6 have been associated with a higher risk of suffering depression." (PMID 30662368, 2018). "The roles of these cytokines are different in RA and lupus, as high IL-10 in RA is associated with increased depressive symptoms, but high IL-10 in the lupus patients is associated with decreased depression." (PMID 30148175, 2018). "IL-10 and IL-6 are likely to be involved, since IL-10 concentration was associated with depression and Tocilizumab decreased depressive symptoms in the RA patients." (PMID 30148175, 2018). "Deprived of the anti-inflammatory effects of exercise, the IL-10 1082 G polymorphism loses its protective influence (and the A allele increases the risk of depression)." (PMID 27555379, 2017). "Contradictory findings on the genetic association between depression and IL-10 have been found by analyzing SNPs of the genomic region of the IL-10 gene cluster." (PMID 27555379, 2017). "TNF-α, IL-6, and IL-10 also played important roles in depression induced by stress, which caused the increase of proinflammation cytokines, including TNF-α, IL-6, and IL-1β in serum and hippocampus." (PMID 28694833, 2017). "In contrast, among male offspring, exposure to higher maternal TNF-α levels relative to IL-10 was associated with a higher risk of depression (OR=1.86; CI=1.02, 3.39)." (PMID 27244231, 2016). "Among female offspring, in utero exposure to higher TNF-α levels relative to IL-10 was associated with a lower risk of depression (OR=0.51; CI=0.32, 0.81)." (PMID 27244231, 2016). "Our finding that the depression risk after exposure to higher prenatal TNF-α:IL-10 levels was restricted to male offspring is consistent with this prior work in male animal models." (PMID 27244231, 2016). "Our results demonstrating that higher pro-inflammatory:anti-inflammatory drive (TNF-α:IL-10 ratio) in maternal serum was associated with a lower risk for depression in female offspring were unexpected." (PMID 27244231, 2016). "Previously, a polymorphism in the promoter region of the IL-10 gene has been associated with poststroke depression, which would be consistent with vulnerability to low IL-10 production among depressed patients." (PMID 25054133, 2014). "These associations further strengthen the interpretation that IL-10 and ion channels are prominent targets for intervention development in medication-refractory depression." (PMID 24143878, 2013).
depression (continued). "Using this approach, our observations reconfirmed dysregulation in two immune genes previously implicated in depression: the cytokines IL-10 and IL-6." (PMID 24143878, 2013). "IL-10 is considered as mainly anti-inflammatory acting and its depression is associated with uncontrolled systemic inflammatory responses." (PMID 24356325, 2013). "Decreased level of IL-10 is associated with depression and more severe somatic depressive symptoms." (PMID 38421829, 2024). "Deficiencies in T-lymphocyte function and IL-10 production may underlie the high comorbidity between pain and depression." (PMID 38646609, 2024). "Results concerning the IL-10 association with depression in CKD are inconsistent." (PMID 37763079, 2023). "We hypothesized that there may be a low Th2 or M2 immune response in pain depression comorbidities since IL-10 is a Th2 or M2-associated cytokine." (PMID 35733107, 2022). "Interestingly, we detected that, after considering the effects of inflammatory mediators (TJC, CRP, and GM-CSF) in regression analyses, IL-10 was inversely associated with depression, fatigue, physio-somatic, and overall PP ratings." (PMID 35330475, 2022). "• Depression is associated with higher concentrations of IL-6, IL-10, TNF-α, and VEGF." (PMID 35836664, 2022). "Additionally, dysregulated levels of GABA, dopamine, 5-HT, and IL-10 have also been shown in anxiety/depression associated with the gut-brain axis." (PMID 33808737, 2021). "Furthermore, our finding that increases in self-reported sleep problems were associated with higher measures of depression, anxiety, IL-5, and IL-10 are similarly consistent with the consensus of these reviews." (PMID 33598780, 2021). "Conventional antidepressants are also known to increase IL-10 levels, with IL-10 being a potent immunoregulatory interleukin capable of suppressing inflammation and changes in the central nervous system (CNS) associated with depression." (PMID 32559185, 2020). "IL-10 rs1518111 was investigated in a study of 167 oncology patients and caregivers and the rare A/A configuration found to be associated with subsydromal depression." (PMID 27555379, 2017). "In contrast, higher TNF-α:IL-10 was linked to a higher risk of depression among males." (PMID 27244231, 2016). "Thus, the balance between TNF-α and IL-10 in maternal prenatal serum was associated with depression in a sex-dependent manner." (PMID 27244231, 2016). "Whether the raised IL10 production is a response to the inflammation associated with depression in our cohort, we found raised IL6 and TNFα only in the hip fracture patients who developed depressive symptoms, remains to be shown but is one possibility." (PMID 26112234, 2016). "Major depression (MD) has been reported to be associated with OS and with inflammation endpoints, namely, excess levels of IL-6, IL-10, and IL-6/IL-10 ratio versus F2-isoprostanes, along with increased protein carbonylation and expression of GR, GPx, SOD, and CAT." (PMID 24876913, 2014). "In addition, the proinflammatory cytokines levels positively correlated with anxiety and/or depression in these patients, while IL-10 negatively associated with such psychological disorders." (PMID 25309921, 2014). "Among subjects with depressive symptoms, higher IL-17 concentrations were associated with lower IL-10 concentrations, suggesting that poststroke depression may be associated with susceptibility to Treg depletion due to a Th17 response." (PMID 25054133, 2014). "Protein elevations of both cytokines in serum and CSF are a consistent finding in depression, with some studies suggesting that IL-6 is specifically associated with medication-refractory depression, and that IL-10 levels decrease following successful treatments." (PMID 24143878, 2013). "In addition, greater depression was associated with higher expression of IL-10 and TRPV4 using QIDS as the severity measure." (PMID 24143878, 2013).
depression (continued). "Anxiety-depression status may cause changes in the IL-1β and IL-10 levels of IBS patients resulting in an imbalance of the proinflammatory and anti-inflammatory cytokines, leading to the occurrence or aggravation of IBS." (PMID 23935726, 2013). "Anxiety-depression status may cause the IL-1β and IL-10 levels in IBS patients to change and result in an imbalance of the proinflammatory and anti-inflammatory cytokines, leading to the occurrence or aggravation of IBS." (PMID 23935726, 2013). "Since an increase in neuronal apoptosis in the hippocampus has been associated with depression in animal models, this putative role of IL-10 in increasing neuronal survival should be investigated as a potential mechanisms of action in preventing depressive-like behavior." (PMID 19936104, 2009). "Interestingly, the depression of these responses was linked to elevated IL-10, which was significantly lower in individuals following treatment who had stable or increased HbA1c levels, supporting this hypothesis." (PMID 37313404, 2023). "IL-10 is a potent anti-inflammatory cytokine released by immune and glial cells that drives the regulation of multiple anti-inflammatory processes, and increasing evidence that pro-inflammatory cytokines are associated with psychiatric disorders, namely depression." (PMID 36120298, 2022). "Dynamic changes in IL-10 levels may thus be associated with the age of onset of depression." (PMID 29856741, 2018). "In the women's sample, lower levels of IL-10, less free time, monthly earnings, and depression were positively correlated with illness count." (PMID 41828624, 2026). "Certain anti-inflammatory proteins, such as IL-10, have also been found to be decreased in individuals with depression." (PMID 39867847, 2025). "It has been suggested that IL-10 levels increase initially in response to acute inflammation as part of the immune system response connected with depression with IL-10 levels eventually decreasing over the course of depression." (PMID 39867847, 2025). "In an in vivo model, tRES-HESP improved memory and depression-like behaviors, reduced cortisol and interleukin (IL)-6 levels, increased IL-10 levels, and lowered the expression of amyloid precursor protein and amyloid beta." (PMID 40362855, 2025). "This aligns with IL-10’s “anti-inflammatory-repair” function, suggesting its potential as a therapeutic target for depression-related cardiovascular protection." (PMID 41327674, 2025). "In our study, a positive correlation was found between IL-10 levels and the severity of depression in patients with PD–T2DM." (PMID 40672460, 2025). "Our findings revealed significantly elevated circulating levels of IL-6, IFN-γ, IL-17, TNF-α, IL-10, and IL-27 in individuals with depression compared to healthy controls." (PMID 41561993, 2025). "IL-8 is also elevated in major depression, while IL-10 and interferon gamma levels vary between early responders and those with treatment resistance." (PMID 40428308, 2025). "In recent years, the roles of pro-inflammatory cytokines (e.g., TNF-α, IL-1β) and anti-inflammatory cytokines (e.g., IL-4, IL-10) in the pathophysiology of depression have been increasingly clarified." (PMID 40453075, 2025). "Escitalopram can reduce the levels of pro-inflammatory cytokines—IL-1β, IL-1ra, IL-2, IL-4, IL-6, IL-8, IFN-y, TNF-α in the serum of patients suffering from depression, while simultaneously increasing the level of anti-inflammatory IL-10." (PMID 41302150, 2025). "IL-10, often considered an anti-inflammatory cytokine, has been shown to play a dual role in depression." (PMID 40305200, 2025). "Among the proinflammatory cytokines associated with depression, IL-6, IL-1β, and TNF-α are most frequently studied, while interleukin-10 (IL-10) acts as a crucial anti-inflammatory factor." (PMID 40520201, 2025).